PRL (prolactin)
Diseases named in the same sentence as PRL in open-access papers (continued):
Sharing a sentence is not in itself a finding about the gene and the disease.
pituitary adenomas (continued). "Pituitary adenomas (PAs) are one of the most common intracranial tumors; approximately half of PAs are prolactin (PRL)‐secreting PAs (prolactinomas)." (PMID 31692290, 2019). "Contrastingly, thyroid cancer had an increased prevalence in patients with growth hormone- (aOR 3.17), prolactin- (aOR 3.66), and thyroid-stimulating hormone-secreting (aOR 6.28) pituitary adenomas (all p < 0.05)." (PMID 31370339, 2019). "The patient was referred to our Neuroendocrine Tumor and Pituitary Unit and he was diagnosed with pancreatic insulinoma, hypercalcemic hyperparathyroidism, and a prolactin secreting pituitary adenoma." (PMID 31249555, 2019). "Stress, the use of drugs affecting the dopaminergic system and macroprolactinemia increase PRL to moderate levels, but pituitary adenomas increase PRL levels significantly." (PMID 30396878, 2019). "The tumors were composed of three main cell populations: One secreting GH, one secreting PRL, and one secreting both hormones, thus leading to the diagnosis of mixed growth hormone/prolactin cell pituitary adenomas." (PMID 31487906, 2019). "The study of the hPRL signaling pathway network is helpful to understand its functions; explore molecular mechanism of PRL-related tumors such as pituitary adenomas, including prolactinomas; develop effective therapeutic drugs; and discover tumor biomarkers." (PMID 30210449, 2018). "Magnetic resonance imaging (MRI) revealed a 2.0 × 2.5 × 2.5 cm pituitary tumor that was presumed to be a functional pituitary adenoma due to the high serum prolactin level." (PMID 29416715, 2018). "Compared to controls, except for variants V2-V6 in PRL-adenomas, V2 in FSH+-adenomas, and V3 in NF−-adenomas, the other PRL variants were significantly downregulated in each subtype of pituitary adenomas." (PMID 30210449, 2018). "In this study, 52 patients were all pathologically diagnosed as prolactin-secreting pituitary adenomas." (PMID 30407358, 2018). "Amongst other abnormalities, lactotrope pituitary adenomas are observed, resulting in an increase in serum prolactin and consequent infertility." (PMID 30410667, 2018). "A functional pituitary adenoma can produce multiple anterior-pituitary hormones, such as growth hormone (GH) -producing adenomas (GHoma) with prolactin or thyrotropin stimulating hormone production in the same lineage." (PMID 28865461, 2017). "In this report, we described a patient who suffered from plurihormonal pituitary adenomas, with concomitant prolactin (PRL) and growth hormone (GH) secretion." (PMID 29245312, 2017). "In patients with PRL pituitary adenomas, PRL levels >200 ng/mL correlated positively with the degree of pituitary adenoma resection." (PMID 29108291, 2017). "MMQ rat prolactinoma cells are traditionally used as a substitutes for human prolactin-secreting pituitary adenoma cells in laboratory experiments, mainly because stably express prolactin (PRL) and have similar biological characteristics." (PMID 28163656, 2017). "In 123 patients with PRL-type pituitary adenomas, patients with large-volume tumors and obvious cavernous sinus invasion had correspondingly high PRL levels." (PMID 29108291, 2017). "Up to 75% of patients with CNC exhibit asymptomatic elevation of GH, IGF-1, or prolactin, and 10% to 12% have acromegaly with detectable pituitary adenoma usually presenting at or after the third decade." (PMID 28973408, 2017). "Pituitary adenomas with acidophilic cells, most of which immunostained for prolactin, presented an overexpression of EG-VEGF." (PMID 28386275, 2017). "Thyrotropin-secreting pituitary adenomas are commonly plurihormonal pituitary adenomas, co-secreting GH, PRL, or both." (PMID 28885368, 2017). "Pituitary adenoma resection had a considerable impact on PRL levels in the present study, which were significantly decreased on first day following surgery, which is consistent with previous studies." (PMID 29108291, 2017).
pituitary adenomas (continued). "Phosphorylated Ser-229 in KDR (pSer-229) levels are significantly higher in noninvasive and invasive prolactin pituitary adenomas compared to normal pituitary tissues." (PMID 27438154, 2016). "(iii) GH3 and AtT-20 represent two distinct pituitary adenoma entities, prolactin and somatotrophin and adrenocorticotropic hormone (ACTH) producing adenoma, respectively." (PMID 27583461, 2016). "Our data indicate that p35 expression and CDK5 activity are both significantly increased in human invasive prolactin pituitary adenomas as compared to noninvasive forms of pituitary adenomas." (PMID 27438154, 2016). "Tissue microarray analysis of pSer229-KDR expression in 48 patients with prolactin pituitary adenomas indicated a significant correlation between high pSer229-KDR expression and poor prognosis." (PMID 27438154, 2016). "We believe that the pituitary adenoma began as ossification due to the autocrine effect of a high prolactin level as well as hemorrhage within the tumor." (PMID 27917338, 2016). "To further examine CDK5 activity, we analyzed the phosphorylation levels of CDK5 in human prolactin pituitary adenomas." (PMID 27438154, 2016). "The prognostic value of pSer229-KDR for recurrence-free survival in prolactin pituitary adenoma patients was evaluated by comparing the patients with weak, moderate, and strong pSer229-KDR expression." (PMID 27438154, 2016). "This resulted in the occurrence of pancreatic beta cell tumours, and pituitary adenomas which immunostained for prolactin in up to 58% of mice." (PMID 26320859, 2016). "To determine the influence of CDK5 on the migration and invasion of prolactin pituitary adenomas, we incubated GH3 rat pituitary cells with either treatments of roscovitine (a CDK5 inhibitor) in different concentrations." (PMID 27438154, 2016). "Endonasal resection, pathology of the tumor, and endocrinology workup revealed a purely ectopic prolactin-secreting pituitary adenoma." (PMID 26885420, 2016). "We found that p35 expression was markedly higher in invasive than in noninvasive prolactin pituitary adenomas." (PMID 27438154, 2016). "Here, we have demonstrated that CDK5 phosphorylates KDR at Ser-229 in prolactin pituitary adenomas, a step that is required for normal cell surface expression of KDR in cell migration and invasion in vitro." (PMID 27438154, 2016). "Most prolactin-secreting pituitary adenomas demonstrate slow growth and are effectively managed with medical/surgical therapy." (PMID 27489751, 2016). "In the current study, we have sought to explore the biological functions of CDK5 and p35 in prolactin pituitary adenomas." (PMID 27438154, 2016). "Expression of p-CDK5 was significantly higher in invasive (mean H-score: 266) than in noninvasive prolactin pituitary adenomas (mean H-score: 194)." (PMID 27438154, 2016). "The most frequent combination immunoprofile was represented by mixt GH and PRL secretion, in fact, resembling the high incidence of composite GH-PRL secretion encountered in single pituitary adenomas." (PMID 26869991, 2016). "Human prolactin pituitary adenomas vary greatly, ranging from small indolent tumors to large invasive ones." (PMID 27438154, 2016). "KDR pSer-229 is upregulated in invasive pituitary adenomas and correlated with poor prognosis in patients with prolactin pituitary adenomas." (PMID 27438154, 2016). "If the pituitary adenoma is a prolactinoma, prolactin levels will dramatically increase (proportional to tumor size)." (PMID 27533614, 2016). "Most of the patients present with a GH and prolactin (PRL)-secreting pituitary adenoma or less commonly GH and PRL cell hyperplasia." (PMID 26982009, 2016). "Identification of new biomarkers that predict the prognosis and therapeutic resistance of prolactin pituitary adenomas is a priority." (PMID 27438154, 2016).
pituitary adenomas (continued). "(36 patients had poly cystic ovary, 24 patients had thyroid disorders, 31 women consumed medicines which affect PRL level, 3 patients had pituitary adenoma and 7 patients had missing data in their records)." (PMID 26000006, 2015). "Reported herein is a 25-year-old woman who was treated for a large and highly atypical prolactin-producing pituitary adenoma." (PMID 26228535, 2015). "Results using [Ca2+]i kinetic assays suggested the existence of a reduced responsiveness of PRL-omas to AG, in that only a low proportion of these pituitary adenoma cells altered their [Ca2+]i in response to AG." (PMID 25737012, 2015). "In tissue sections, prolactin (PRL)-producing pituitary adenomas typically present as monotonous arrays of chromophobic cells in diffuse, papillary, or sinusoidal proliferations." (PMID 26228535, 2015). "The immunohistochemistry was PRL positive and confirmed the lesion to be a PRL-type pituitary adenoma." (PMID 26220796, 2015). "A final diagnosis of PRL-producing pituitary adenoma was reached after considering the immunohistochemical profile, suprasellar location, and prolactin production of the tumor, as well as the absence of metastatic foci and invasion into surrounding tissue." (PMID 26228535, 2015). "Approximately one-third of TSH-secreting pituitary adenomas co-secrete other hormones, the most common of which is growth hormone (GH) (16%) followed by prolactin (11%) and gonadotropins (1%)." (PMID 25614823, 2015). "Multihormonal tumor cells producing GH and TSH have been isolated from patients affected by acromegaly and hyperthyroidism and cells co-secreting GH and PRL have been described in pituitary adenomas from acromegalics." (PMID 26106585, 2015). "All pituitary adenomas were derived from the pars distalis, as determined by expression of prolactin." (PMID 25136513, 2014). "These transgenic mice developed lactotroph hyperplasia at 6 months of age and prolactin-producing pituitary adenomas with high penetrance by 12 months of age." (PMID 25136513, 2014). "Transgenic mice expressing high levels of the HMGA2 transgene in all tissues (by using the cytomegalovirus promoter) developed mixed growth hormone/prolactin cell pituitary adenomas with high penetrance (85% of female animals) by 6 months of age." (PMID 25136513, 2014). "HMGA2 was frequently upregulated in pituitary adenomas including PRL, ACTH, FSH/LH, or null cell adenomas but relatively rare in GH and mixed GH/PRL adenomas." (PMID 25548562, 2014). "It is well known that GH-producing pituitary adenomas often coexpress prolactin (PRL) and, less frequently, thyroid stimulating hormone (TSH)." (PMID 23401791, 2013). "In this study, we demonstrate that Magmas exerts protective effects towards apoptotic stimuli not only in a mouse ACTH-secreting pituitary adenoma cell line, but also in a rat GH/PRL secreting pituitary adenoma cell line." (PMID 24069394, 2013). "The prolactin type of pituitary adenoma was the most frequent (eight cases), in addition, there were two cases of ACTH (including the present case) and one case of thyroid-stimulating hormone; the remaining cases were the nonfunctional or silent type." (PMID 23919255, 2013). "Cabergoline seems to be safe and effective in the treatment of prolactin and growth hormone cosecreting pituitary adenomas as well as prolactinomas." (PMID 23762662, 2013). "Herein, we describe the case of a woman with an extremely large pituitary adenoma cosecreting prolactin and growth hormone (GH) who is treated successfully only with cabergoline as a first line treatment." (PMID 23762662, 2013). "Magmas over-expression in rat GH/PRL-secreting pituitary adenoma GH4C1 cells leads to an increase in cell viability and to a reduction in staurosporine-induced apoptosis and DNA fragmentation, in parallel with the increase in Magmas protein expression." (PMID 24069394, 2013).
pituitary adenomas (continued). "We report a rare case of pituitary adenoma with concomitant corticotroph, prolactin, and growth hormone staining cells, review literature on similar cases, and discuss possible biological mechanisms underlying these plurihormonal tumors." (PMID 23320206, 2012). "After treatment with L-T4, plasma T3, T4, TSH, PRL and menstruation returned to their normal ranges, and the large pituitary adenoma disappeared in MRI scan." (PMID 22527578, 2012). "Pituitary adenomas are common monoclonal neoplasms accounting for approximately twenty percent of primary intracranial tumors with prolactin-secreting pituitary adenomas (prolactinomas) and are the most common form of pituitary tumors in humans." (PMID 27340590, 2012). "Pharmacological treatment of pituitary adenomas by cabergoline primarily aims at inhibition of prolactin stimulation, leading to the involution of prolactinomas." (PMID 22273876, 2012). "Among GH-secreting pituitary adenomas, roughly 60% are pure GH-secreting somatotrope adenomas, while the remainder are mixed mammosomatotropes, which secrete both GH and prolactin (PRL) and sometimes thyroid-stimulating hormone (TSH)." (PMID 22518132, 2012). "Next, we investigated for the first time the effect of rhEPO administration on pituitary adenomas using a nude mouse xenograft model of rat MMQ prolactin-secreting pituitary adenoma cells." (PMID 22086127, 2012). "Trans-sphenoidal surgery for pituitary adenomas was evaluated in 27 uncontrolled studies and was found to be effective in normalizing prolactin levels and resolving symptoms." (PMID 22828169, 2012). "This prompted that the large pituitary adenoma was caused by the hyperplasia and hypertrophy of TSH and PRL secreting cells." (PMID 22527578, 2012). "It has been suggested that in female rats, continuous exposure to moderately increased or medium levels of estrogens unopposed by progesterone leads initially, to increased PRL secretion and later to the development of PRL-secreting pituitary adenomas." (PMID 21799890, 2011). "After transsphenoidal resection, a pituitary adenoma showing cytoplasmic immunoreactivity to prolactin was identified." (PMID 22011738, 2011). "The pituitary adenoma represents a complex heterogeneous mixture of cells including prolactin (PRL), endothelial cells, fibroblasts, and other stromal cells." (PMID 20205839, 2010). "Our team had finished the experiment to get prolactin cells by LCM from paraffin embodied pituitary adenoma samples and the proteins number was nearly equal to that from frozen samples (data not shown)." (PMID 20205839, 2010). "The serum prolactin concentration was increased (1751 ng/mL; normal, 1.4 to 14.6), and a large pituitary adenoma was apparent on computed tomography (CT)." (PMID 21034446, 2010). "Further studies are needed to elucidate the pathogenesis of different subtype pituitary tumors including GH-secreting pituitary adenomas, PRL-secreting pituitary adenomas, and corticotropinoma." (PMID 21138567, 2010). "A large pituitary adenoma with an increased level of serum prolactin was apparent by computed tomography." (PMID 21034446, 2010). "The existence of a primordial cell in the pituitary was proposed more than ten years ago when exceptional human pituitary adenomas were observed to concomitantly express Pit1-dependent hormones (GH, PRL and TSH) plus ACTH and gonadotrophic hormones." (PMID 19283075, 2009). "Adrenal hyperandrogenism is uncommon and seen in congenital adrenal hyperplasia, late-onset adrenal hyperplasia, Cushing's syndrome, pituitary adenomas that produce excess corticotropin or prolactin and acromegaly." (PMID 19882006, 2008). "In the female rat, we have shown that aging is characterized by a high incidence of prolactin secreting pituitary adenomas and diffuse prolactin cell hyperplasia." (PMID 17222350, 2007). "Prolactinomas, prolactin-secreting pituitary adenomas, are the most frequently found functional pituitary tumors in humans." (PMID 17331262, 2007).
pituitary adenomas (continued). "The identification of AIP as a candidate tumour-suppressor gene, lost in both GH and PRL-secreting pituitary adenomas, prompted us to study its possible involvement in other tumour types." (PMID 17242703, 2007). "Bromocriptine is commonly chosen as a therapeutic agent for patients with prolactinomas or other pituitary adenomas; bromocriptine binds to the dopamine D2 receptor on pituitary epithelial cells to inhibit prolactin secretion." (PMID 17331262, 2007). "These patients have prolactin (PRL) or growth hormone (GH) oversecreting pituitary adenomas, the latter exhibiting acromegaly or gigantism." (PMID 17242703, 2007). "In fact, transgenic mice expressing high levels of the HMGA2 gene develop pituitary adenomas secreting prolactin and growth hormone." (PMID 16914062, 2006). "Overexpression of HMGA2 gene leads to the onset of prolactin and GH-hormone induced pituitary adenomas in mice, suggesting a critical role of this protein in pituitary tumorigenesis." (PMID 16914062, 2006). "The expression of Magmas was also shown to induce a protective role against the apoptotic stimulus of the protein kinase C (PKC) inhibitor staurosporine in the murine ACTH-secreting pituitary adenoma cell line and the rat pituitary adenoma cell line-secreting growth hormone/prolactin (GH/PRL)." (PMID 40358179, 2025). "Ongoing follow-up of prolactin levels and titration of DA post-operatively should be performed by the endocrinologist, in addition to the usual post-operative biochemical monitoring that is standard of care for all pituitary adenomas." (PMID 40004619, 2025). "Mixed ACTH- and PRL-secreting pituitary adenomas, although extremely rare, do occur and may lead to both Cushing’s syndrome and galactorrhea/oligo- or amenorrhea syndrome." (PMID 41201503, 2025). "However, to potentially identify patients with a higher PRL concentration, we separately examined patients with a concurrent diagnosis of pituitary adenoma and those managed at a university hospital." (PMID 40478803, 2025). "There are case reports where myasthenia gravis has been associated with pituitary adenomas, commonly prolactin-secreting adenomas, non-functioning adenomas, and growth hormone-secreting adenomas, but never presenting simultaneously with pituitary apoplexy." (PMID 40236367, 2025). "Elevated plasma prolactin may also indicate the presence of a pathologic process, such as pituitary stalk compression or a prolactin-secreting pituitary adenoma." (PMID 38698869, 2024). "However, from a clinical point of view, the management of pituitary adenomas with markedly increased prolactin (prolactinoma) and with normal prolactin (NFPA) is completely different." (PMID 39051300, 2024). "Three of them were gonadotroph adenoma, 3 corticotropic adenoma, 3 GH and prolactin producing pituitary adenoma, 2 were plurihormonal pituitary adenoma, 4 with atypical sparsely granulated GH-producing pituitary adenoma, and 1 patient was not categorized into it." (PMID 39677352, 2024). "In general, prolactin levels correlate well with pituitary adenoma size." (PMID 38645431, 2024). "Patients with PRL-secreting pituitary adenomas have increased plasma concentrations of dehydroepiandrosterone sulphate (DHEAS) and whilst dopamine agonists reduce both serum PRL and DHEAS concentrations, they do not inhibit adrenocorticotropic releasing hormone secretion (ACTH)." (PMID 39000207, 2024). "These pituitary adenomas are usually functional, secreting GH (80%) or both GH and prolactin." (PMID 38479600, 2024). "Testosterone concentrations, albeit rarely, may be in the normal range (>3.0 ng/mL) in men with a prolactin-secreting pituitary adenoma (PSPA-nt)." (PMID 39109291, 2024). "Consequently, proactive management of GH and PRL levels preoperatively facilitates heightened rates of remission for growth hormone and prolactin post pituitary adenoma resection." (PMID 37964947, 2023). "MET level was increased in prolactin-releasing human pituitary adenomas." (PMID 37509632, 2023).